AQP3 (aquaporin 3 (Gill blood group))
Diseases named in the same sentence as AQP3 in open-access papers (continued):
Sharing a sentence is not in itself a finding about the gene and the disease.
CMV infection (1 paper, 2020). "Our present study revealed the AQP3 A(−1431)G promoter polymorphism as a novel promising and independent genetic risk factor for CMV infection." (PMID 32521638, 2020). "One-year CMV infection risk was significantly associated with the AQP3 A(−1431)G genotypes (p = 0.013)." (PMID 32521638, 2020). "Restricted model confirmed AQP3 promotor polymorphism as the strongest and sole risk factor for CMV infection (p = 0.023)." (PMID 32521638, 2020). "To analyze potential in vivo impacts of the AQP3 polymorphism on disease course, including graft rejection and CMV infection, we analyzed clinicopathological parameters in the study patients post-transplantation." (PMID 32521638, 2020). "The impact of the AQP3 A(−1431)G promoter polymorphism in kidney transplant recipients was unelucidated and we explored the effect of AQP3 polymorphism on immune cell function and its association with graft rejection and CMV infection in 237 adult patients within 12 months after transplantation." (PMID 32521638, 2020). "However, for the given indication, the study population was not small and multivariate Cox regression analyses revealed the AQP3 A(−1431)G polymorphism as an important and strong prognostic factor for one-year graft rejection and CMV infection." (PMID 32521638, 2020). "Therefore, we tested the hypothesis that the AQP3 A(−1431)G promoter polymorphism is functionally active, alters immune cell migration and AQP3 expression in T-cells, and is associated with acute rejection and CMV infection after kidney transplantation." (PMID 32521638, 2020). "Major complications after kidney transplantation are graft rejection and cytomegalovirus (CMV) infection, which are related to T-cell function, which depends on aquaporin 3 (AQP3) expression." (PMID 32521638, 2020). "Due to the high complexity of the immune response to CMV infection, we can only speculate about the main AQP3 expression-related effector." (PMID 32521638, 2020). "However, AQP3 is highly expressed in T-lymphocytes, which play an important role in the immune response to CMV infection, and its expression might be essential for T-cells activity, as confirmed by the current study." (PMID 32521638, 2020).
corneal disease (1 paper, 2024). "AQP3 expression may also be related to corneal disease since in PBK corneas, and Fuchs’ dystrophy AQP3 is reportedly upregulated compared to normal corneas; however, the reason for this change is unclear." (PMID 38612559, 2024).
dental caries (1 paper, 2026). The decay of a tooth, in which it becomes softened, discolored, and/or porous. "This study aimed to investigate the association between salivary AQP3 expression and dental caries and periodontal parameters, evaluating its potential as a biomarker for oral health and disease." (PMID 41882662, 2026).
diabetic nephropathy (1 paper, 2022). "Regarding the cause of end-stage kidney disease, AQP3 expression positively correlated with erythropoietin dosages in the chronic glomerulonephritis (GN) subgroup (R = 0.6; P = 0.003), but negatively in the diabetic nephropathy subgroup (R = -0.59; P = 0.004)." (PMID 36038817, 2022).
dilated cardiomyopathy (1 paper, 2018). Cardiomyopathy which is characterized by dilation and contractile dysfunction of the left and right ventricles. "KEGG pathway analysis on cardiac loop genes reveals enrichments for terms, such as dilated cardiomyopathy, vasopressin-regulated water reabsorption, and hypertrophic cardiomyopathy (the genes within these terms include: Adcy6, Aqp3, Creb3l4, Des, Itgb5, Itga9, Myl2, Myl3, and Stx4a)." (PMID 30697540, 2018).
E. coli infection (1 paper, 2025). "Additionally, LR treatment in the broiler diet alleviated the reduced mRNA expression of AQP3 in the jejunal and ileal mucosa under E. coli infection." (PMID 41514770, 2025).
endothelial dysfunction (1 paper, 2018). In vascular diseases, endothelial dysfunction is a systemic pathological state of the endothelium (the inner lining of blood vessels) and can be broadly defined as an imbalance between vasodilating and vasoconstricting substances produced by (or acting on) the endothelium. "Moreover, AQP3, although being a functional aquaglyceroporin that contributes to endothelium glycerol permeation, seems not to contribute to the development of ADA-induced endothelial dysfunction." (PMID 29301341, 2018).
endotoxemia (1 paper, 2019). "The higher serum osmolality in AQP1-KO mice during endotoxemia in the absence of water repletion was associated with higher AQP2, AQP3, and Na+-K+-2Cl− cotransporter type 2 expression and a lower Na+/H+ exchanger type 3 protein expression than that in WT mice during endotoxemia." (PMID 31023968, 2019).
eosinophilia (1 paper, 2016). "Especially, a substantial reduction in eosinophilia, characteristic in allergic inflammation, was observed in BALF of AQP3−/− mice." (PMID 27165276, 2016).
extramammary Paget disease (1 paper, 2021). A malignant neoplasm in which there is infiltration of the skin by neoplastic large cells with abundant pale cytoplasm and large nuclei with prominent nucleoli (Paget cells). "All 24 solar keratoses and 16 extramammary Paget's diseases showed diffuse AQP3 staining." (PMID 34745849, 2021). "Diffuse AQP3 expression was also present in all extramammary Paget's disease." (PMID 34745849, 2021).
gallstones (1 paper, 2023). Solid crystalline precipitates in the biliary tract, usually formed in the gallbladder, resulting in the condition of cholelithiasis. "Data from our study highlight the inhibitory role of AQP3 in gallbladder damage and gallstone formation in mice by reducing inflammatory injury of gallbladder mucosal epithelial cells, which is achieved through activation of the AMPK/SIRT1 signaling pathway." (PMID 37641009, 2023). "Therefore, further research is needed to explore and verify the mechanism of action of AQP3 in gallstone formation." (PMID 37641009, 2023).
gastric diseases (1 paper, 2012). "H. pylori infection dose- and time-dependently increased the protein levels and transcription of AQP3, indicating that AQP3 may be involved in H. pylori infection-related gastric diseases." (PMID 23152856, 2012). "Based on our previous findings, we speculated that AQP3 may play an important role in H. pylori-related gastric diseases." (PMID 23152856, 2012).
hydrocele (1 paper, 2014). "Frozen tunica vaginalis specimens from patients with adult-onset primary hydrocele testis and control male nonhydrocele patients were subjected to Western blot analysis for the detection of AQP1 and AQP3 proteins." (PMID 24817884, 2014).
hydrops (1 paper, 2020). "Therefore, the present hydrops formation may have resulted from the acceleration of endolymphatic water homeostasis via glucocorticoid-enhanced AQP3 in the inner ear." (PMID 33505985, 2020).
infectious diarrhoea (1 paper, 2025). "Similarly, downregulation of Aqp3 is associated with inflammatory and infectious diarrhoea, and Aqp3−/− mice exhibit diminished populations of Th17 and Treg cells." (PMID 41361166, 2025).
inflammatory breast carcinoma (1 paper, 2008). An advanced, invasive breast adenocarcinoma characterized by the presence of distinct changes in the overlying skin. "WalBC also exhibited overexpression of AQP3 which is associated with inflammatory breast cancer." (PMID 18179684, 2008).
Insulin resistance (1 paper, 2019). Increased resistance towards insulin, that is, diminished effectiveness of insulin in reducing blood glucose levels. "The expression of desmosomal molecules, cell cycle regulatory molecules, and AQP3 was not significantly altered, suggesting that these molecules were affected by factors other than insulin resistance." (PMID 31581253, 2019).
kidney cancer (1 paper, 2023). Primary or metastatic malignant neoplasm involving the kidney. "The GDC data Portal of the National Cancer Institute reports four cases of kidney cancer (three females and one male) where AQP3 was found to be mutated." (PMID 38132440, 2023).
larynx squamous cell carcinoma (1 paper, 2022). "Its upregulation reduced cell viability in cisplatin-resistant tongue and larynx squamous cell carcinoma cell lines by downregulating the genes for aquaporin-3 (AQP3), caspase-14 (CASP-14) and arachidonate 12R-lipoxygenase (ALOX12B)." (PMID 36287119, 2022).
lentivirus infection (1 paper, 2021). Virus diseases caused by the Lentivirus genus. "A lentivirus infection system was used to construct stable cell lines with either AQP3 knockdown or overexpression." (PMID 33781292, 2021).
lipid metabolic disorders (1 paper, 2023). "Additionally, mice given HFD showed a considerable downregulation of the AQP-4 gene in the kidney, which Kuhns and Pluznick (2018) hypothesized that it was caused by an increase in cellular ROS generation resulting from lipid metabolic disorders, similarly to AQP-3 expression." (PMID 38357327, 2023).
liver cirrhosis (1 paper, 2018). "Moreover, high levels of AQP3 were associated with liver cirrhosis (p = 0.039) and gross vascular invasion (GVI, p = 0.017)." (PMID 29415990, 2018).
lupus (1 paper, 2025). "The authors reported an increase in AQP1 expression in lupus glomeruli and a decrease in AQP1, AQP2, and AQP3 expression in renal tubules based on immunohistochemistry (IHC)." (PMID 40072108, 2025).
lupus nephritis (1 paper, 2025). Glomerulonephritis in the context of systemic lupus erythematosus. "Further research is warranted to evaluate AQP1, AQP2, and AQP3 as prognostic markers in both urinary and histological assessments of lupus nephritis." (PMID 40072108, 2025). "The aim of this study is to characterize the tubular expression of AQP1, AQP2 and AQP3, which could provide a better understanding of tubulointerstitial stress during lupus nephritis." (PMID 40072108, 2025). "In lupus nephritis (LN), although we observed a reduction in staining for AQP1, AQP2, and AQP3; their localization remained unchanged." (PMID 40072108, 2025). "A 2003 study performed using several types of glomerulonephritis including 4 lupus nephritis suggested a decrease in the expression of AQP2 and AQP3 and an increase in the expression of AQP1 in pathological glomeruli." (PMID 40072108, 2025).
lymphedema (1 paper, 2024). Excess fluid collection in tissues, causing swelling. "The experimental results showed that TRPML1 affects the membrane localization of AQP3, -5 in direct correlation with the alteration of lymphatic endothelial cell water permeability, which is inevitably associated with the development of lymphedema." (PMID 39637010, 2024). "Following induction of the lymphedema model, the lymphedema tissue of mice was retained, and the gene expression changes of AQP3, -5 were detected by qPCR using the SHAM group as the control group." (PMID 39637010, 2024). "Our results provide primary evidence that TRPML1 regulates the cell membrane localization of AQP3, -5 in HLECs, resulting in enhanced permeability and the development of lymphedema, as accompanied by chronic inflammation." (PMID 39637010, 2024). "This further demonstrates that the activation of TRPML1 enhances the water permeability of HLECs by mediating the membrane aggregation of AQP3, -5, contributing to the pathological process of lymphedema." (PMID 39637010, 2024). "Further studies are needed to investigate the pathological mechanism of the role of AQP3, which is more dominantly expressed in HLECs, in influencing lymphedema." (PMID 39637010, 2024). "This study addresses a research gap concerning TRPML1 and AQP3, -5 in lymphedema inflammation." (PMID 39637010, 2024). "This implies that TRPML1 does not directly influence lymphedema through modulating AQP3, -5 protein expression levels." (PMID 39637010, 2024). "Our results indicate that TRPML1 not only regulates the localization of AQP3, -5 to the cell membrane but also increases HLEC permeability, disrupts lymphatic fluid transport, and mediates the development of chronic inflammation at the site of lymphedema." (PMID 39637010, 2024).
lymphoma (1 paper, 2018). A malignant (clonal) proliferation of B- lymphocytes or T- lymphocytes which involves the lymph nodes, bone marrow and/or extranodal sites. "The AQP3 gene single-nucleotide polymorphism locus of aquaporin 3 (rs2231231) is associated with a susceptibility to Epstein-Barr virus (EBV)-associated nasopharyngeal carcinoma EBVaNPC and lymphoma EBVaL." (PMID 30555637, 2018).
medullary thyroid carcinomas (1 paper, 2012). "Therefore, we suggest that AQP3 may be associated with the biological nature of human medullary thyroid carcinoma cells." (PMID 22808259, 2012). "Reverse transcriptase polymerase chain reaction (RT-PCR) analyses revealed AQP3 mRNA expression only in medullary carcinomas and AQP4 mRNA expression in follicular cell-derived tumors except for undifferentiated carcinomas." (PMID 22808259, 2012). "We specifically observed expression of AQP3 mRNA in the TT cell line which was established from human medullary carcinoma." (PMID 22808259, 2012). "In neoplastic thyroid tissues, immunoreactivity of AQP3 was frequently demonstrated in the cytoplasmic membrane of medullary carcinoma cells." (PMID 22808259, 2012). "Among 20 medullary carcinomas positive for AQP3, the distribution patterns of AQP3-positive cells varied: 55% (11/20) in diffuse, 40% (8/20) in intermediate, and 5% (1/20) in focal medullary carcinomas." (PMID 22808259, 2012). "In neoplastic thyroid tissues, we identified AQP3 mRNA expression only in medullary carcinomas." (PMID 22808259, 2012). "In addition, we found AQP3 expression in the TT cell line which originates from human medullary carcinoma." (PMID 22808259, 2012). "The overall positive frequency of AQP3 in medullary carcinomas was 91% (20/22)." (PMID 22808259, 2012). "Our data suggest that AQP3 might be involved with calcium metabolism in medullary thyroid carcinoma cells." (PMID 22808259, 2012). "In this study, we demonstrated that AQP3 was positive in most medullary thyroid carcinomas and negative in follicular cell-derived tumors using immunohistochemistry in conjunction with RT-PCR." (PMID 22808259, 2012). "In neoplastic thyroid lesions, we observed AQP3 in 91% of medullary thyroid carcinomas but in no other follicular cell tumors." (PMID 22808259, 2012).
multinodular goiter (1 paper, 2012). Nodular goiter characterized by more than one discrete tissue mass. "We also failed to demonstrated immunopositivity of AQP3 in hyperplastic follicular cells of Graves’ disease thyroids and multinodular goiters." (PMID 22808259, 2012).
multiple myeloma (1 paper, 2025). "Recently, DFP00173 was found to reduce multiple myeloma cell viability, tumor growth, mitochondrial respiration and electron transport chain complex I activity through AQP3 blockage." (PMID 39941100, 2025). "In addition, the anti-AQP3 monoclonal antibody was found to reduce multiple myeloma cell viability, tumor growth, mitochondrial respiration and electron transport chain complex I activity via AQP3 inhibition." (PMID 39941100, 2025).
Myocardial fibrosis (1 paper, 2023). "It is hypothesized that AQP3 might alleviate myocardial fibrosis and HF via the reduction in the MMP expression level and degradation of the ECM." (PMID 37143707, 2023).
myocardial infarct (1 paper, 2015). "In order to determine if infarct size reduction was a generalized phenomenon in the AQP deficient mice, we also induced MI in AQP3−/− mice and measured myocardial infarct sizes." (PMID 26348407, 2015).
non-alcoholic steatohepatitis (1 paper, 2018). "We further explored the role of AQP3 in primary HSCs isolated from patients with non-alcoholic steatohepatitis (NASH), showing an upregulation of its protein and gene expression, which was proportional to the fibrosis stage, by PPARγ through the c-Jun N-terminal kinase (JNK) pathway." (PMID 29914059, 2018).
oral lichen planus (1 paper, 2023). Oral lichen planus is a chronic inflammatory oral condition of unknown aetiology characterized by T-cell-mediated chronic immune response and abnormal epithelial keratinization cycle. "In the occurrence of mucosal injury, upregulation of AQP3 expression could make compensation for the mucosal injury and delay the disease progression of oral lichen planus." (PMID 37641009, 2023).
Polydipsia (1 paper, 2019). Excessive thirst manifested by excessive fluid intake. "The primary polydipsia associated with the inhibition of ACE declined inner medullary aquaporin (AQP) 2, without significant change AQP3 and AQP4 expression." (PMID 31116771, 2019).
proliferative glomerulonephritis (1 paper, 2025). A constellation of renal disorders characterized by an increase number of cells in the glomerulus; these disorders generally present with nephrotic syndrome, and generally progress to end stage renal failure over a matter of weeks to years, depending on the etiology. "In the subgroup of proliferative glomerulonephritis (class III/IV), this decrease in AQPs expression was more pronounced, particularly for AQP3." (PMID 40072108, 2025).
prostate tumors (1 paper, 2010). "A large subgroup of primary prostate tumors has reduced levels of AQP3 and AQP1 as most of the lymph node metastasis samples." (PMID 20805891, 2010).
pulmonary diseases (1 paper, 2022). "Considering the role of AQP3-mediated water transport in the airways, increasing AQP3 expression through modulation with corticosteroids as dexamethasone and ambroxol could exert a therapeutic effect on pulmonary diseases with airway hypersecretion through clearance of pulmonary fluid." (PMID 35187089, 2022).
rectal cancer (1 paper, 2020). A primary or metastatic malignant neoplasm that affects the rectum. "However, neither AQP3 nor AQP5 were correlated with ADCaqp value, which may indicate that AQP1 is mainly responsible for water transport through membranes in rectal cancer." (PMID 32576929, 2020).
salivary gland tumors (1 paper, 2020). "A few studies have also evaluated the expression of AQPs in the development and progression of salivary gland tumors, with special attention given to AQP3 and AQP5, because they are the predominant AQPs of normal salivary gland tissue." (PMID 32075009, 2020).
sebaceous adenoma (1 paper, 2021). A benign, well circumscribed neoplasm arising from the sebaceous glands. "Sebaceous carcinoma shows no expression of AQP3 whereas benign sebaceous lesions including sebaceous hyperplasia, sebaceous adenoma, and sebaceoma all show retained expression of AQP3, suggesting that loss of AQP3 may contribute to the carcinogenesis of sebaceous carcinoma." (PMID 34745849, 2021). "Among sebaceous tumors, AQP3 expressed diffusely in all sebaceous hyperplasia and sebaceous adenoma, but not in sebaceous carcinomas." (PMID 34745849, 2021). "In our study, we found the diffuse positivity pattern of AQP3 expressed in all sebaceous hyperplasias and sebaceous adenomas, but not in sebaceous carcinomas." (PMID 34745849, 2021).
sebaceous tumors (1 paper, 2021). "Therefore, AQP3 immunohistochemical staining may have some value for distinguishing benign sebaceous tumors from malignant ones." (PMID 34745849, 2021).
skin rashes (1 paper, 2024). "To evaluate the relationship between adapalene concentrations and skin rashes, we investigated the expression of AQP3, which is present in the outer epithelial layer of the skin, by RT–PCR." (PMID 38379420, 2024).